OTUD1 (OTU deubiquitinase 1)
Diseases named in the same sentence as OTUD1 in open-access papers (continued):
Sharing a sentence is not in itself a finding about the gene and the disease.
triple-negative breast carcinoma (1 paper, 2018). An invasive breast carcinoma which is negative for expression of estrogen receptor (ER), progesterone receptor (PR), and human epidermal growth factor receptor 2 (HER2). "Compared with HEK293A cells, triple-negative breast cancer cell lines such as BT549 and the LM2 lung-metastatic subline of MDA-MB-231 cells showed much lower levels of OTUD1 protein." (PMID 29891922, 2018).
type 2 diabetes (1 paper, 2023). "Dapagliflozin, an SGLT-2 inhibitor for type 2 diabetes treatment, reportedly has the potential to inhibit OTUD1, and its binding model has also been proposed." (PMID 36829909, 2023).
tumor (21 papers, 2017 to 2025). "OTUD1 facilitated the release of damage-associated molecular patterns (DAMPs), which in turn recruited tumor-responsive T cells and curbed colon cancer progression." (PMID 40469292, 2025). "As a result, genes encoding ubiquitin conjugating enzymes or ligases, such as UBE2T, UBE2C, and CBLC, were up‐regulated in tumor tissues, while genes encoding deubiquitinating enzymes like OTUD1 and USP12 were down‐regulated." (PMID 37983609, 2024). "Mechanistically, tumor-associated macrophages (TAMs) activate NF-ĸB by secreting TNFα/IL-1β in the liver microenvironment and transcriptionally upregulate OTU deubiquitinase 1 (OTUD1) expression, which enhances FGL1 stability via deubiquitination." (PMID 37872170, 2023). "Recent evidence has highlighted the host anti-tumor immunity of OTUD1 as it can potentiate the release of damage-associated molecular patterns, which in turn recruits the leukocytes and strengthens host immune response." (PMID 36182943, 2022). "Moreover, a recent study based on glioma cases showed that the increased expression of OTUD1 in tumor associated-macrophages is associated with a risk of poor prognosis, although the detailed cellular mechanism is unknown." (PMID 36829909, 2023). "Previous studies have highlighted the role of various DUBs in tumor progression, with OTUD1 recognized as a key tumor suppressor." (PMID 40664662, 2025). "As a member of this family, OTUD1 has shown tumor-suppressive effects in cancers such as lung and liver cancer, but its role in NPC remains unexplored, warranting further research." (PMID 40664662, 2025). "Relative to control cells, cells with OTUD1 knockout (KO) resulted in compromised tumor sphere formation, soft agar colony formation and tumor cell invasion ability." (PMID 38351029, 2024). "Melatonin markedly reduces tumor growth and size with increased apoptosis of cancer cells, and the expression levels of Bim and OTUD1 are correlated in patients with renal clear carcinoma." (PMID 36829909, 2023). "Consistently, half-life analysis using cycloheximide pulse-chase analysis showed that downregulation of OTUD1 attenuated the protein half-life of FGL1 in tumor cells cultured with TAM-CM." (PMID 37872170, 2023). "Mechanistically, we reveal that tumor-associated macrophages (TAMs) mediate the stabilization of FGL1 through nuclear factor kappa-B (NF-ĸB) activation and OTU deubiquitinase 1 (OTUD1) expression in the liver microenvironment." (PMID 37872170, 2023). "Evidence exists suggesting tumor-inhibiting properties of deubiquitylase OTUD1 in various malignancies." (PMID 36182943, 2022). "In the in vivo settings, the effect of differential OTUD1 expression on tumor growth was even more pronounced." (PMID 36357400, 2022). "Focused CRISPR screen, transcriptional and proteomic analysis identify deubiquitinase OTUD1 as a critical mediator of Ig synthesis, proteasome inhibitor sensitivity and tumor burden in MM." (PMID 36357400, 2022). "Immunohistochemical (IHC) results illustrated that Ki67 positive cells were fewer in the tumor tissues of mice treated with oe-OTUD1 while much more fewer Ki67 positive cells were detected when OTUD1 was overexpressed in the presence of erlotinib." (PMID 36182943, 2022). "We herein investigated the anti-tumor effect and clarified the downstream mechanisms of OTUD1 in the chemoresistance of non-small cell lung cancer (NSCLC) cells." (PMID 36182943, 2022). "OTUD1 inhibits breast cancer metastasis by reducing TGF-β-induced tumor-promoting responses by deubiquitinating SMAD7." (PMID 35642058, 2022). "In contrast, the expression levels of OTUD1 and NF-κB1 were correlated in both the normal and tumor kidney cortexes." (PMID 35941131, 2022). "Statistical analysis confirmed that silencing of OTUD1 increases the frequency of tumor-initiating cells." (PMID 29235476, 2017).
tumor (continued). "Inactivation of OTUD1 promoted tumor incidence and tumor growth and shortened latency after injection of limiting numbers of MCF10A-RAS cells in mice." (PMID 29235476, 2017). "Moreover, OTUD1-mediated tumor regression was observed in BALB/c mice injected with CT26 cells but not in NOD-SCID mice, indicating immune-dependent tumor clearance." (PMID 40607253, 2025). "We hypothesized that modifying the methylation state could restore TFAP2C and OTUD1 expression, thus enhancing tumor cell radiosensitivity." (PMID 40664662, 2025). "Finally, a mouse xenograft tumor model was used to determine the effects of OTUD1 KO on tumorigenesis in vivo." (PMID 38351029, 2024). "Thus, OTUD1 functions as a tumor suppressor and contributes to the efficacy of erlotinib in NSCLC through the YAP/SOX9/SPP1 axis." (PMID 36829909, 2023). "Therefore, the OTUD1–PTEN axis suppresses tumor growth and regulates the resistance of ccRCC to tyrosine kinase inhibitors." (PMID 36829909, 2023). "In conclusion, our study reveals that OTUD1 potentially acts as a tumor suppressor and suppresses erlotinib resistance of NSCLC through the YAP1/SOX9/SPP1 axis, suggesting that OTUD1 may serve as a target for reducing chemoresistance for NSCLC." (PMID 36182943, 2022). "Moreover, we showed that OTUD1 was not only downregulated in the KIRC tumor tissues but was also decreased along with increased KIRC tumor stage and grade." (PMID 35280681, 2022). "Moreover, OTUB1 and OTUD1 act as tumor suppressors in breast cancer." (PMID 39678489, 2024). "Furthermore, the nude mouse studies showed that OTUD1 depletion led to tumor growth in vivo." (PMID 35280681, 2022). "However, the depletion of DCAF10 rescued the tumor suppression of ectopic OTUD1 expression in K244R mutant cells (comparing K244R&D1&shDCAF10 to K244R&D1), which is due to the inhibition of the MCL1 downregulation‐induced caspase‐dependent apoptosis pathway and AIF release (parthanatos)." (PMID 33898171, 2021). "Our research found that OTUD1 stabilizes the mitochondrial protein SLC25A11, elevating ROS levels and inducing oxidative stress, which leads to tumor cell apoptosis." (PMID 40664662, 2025). "OTUD1, a deubiquitinase from the OTU protein family, is essential in regulating antiviral host defence, tumour progression and inflammation." (PMID 39118286, 2024). "Relatively, OTUD1 also can inhibit tumor metastasis by preventing the degradation of SMAD family member 7 (SMDA7), which can inhibit tumor metastasis by blocking TGF-β signaling pathway." (PMID 37251574, 2023). "OTUD1 suppresses resistance to erlotinib, an epidermal growth factor receptor tyrosine kinase inhibitor, in NSCLC cells and tumor-bearing mice." (PMID 36829909, 2023). "In PAAD, the expressions of OTUD1 (P = 1.06E−52), YOD1 (P = 2.20E−50) and OTUD5 (P = 1.53E−45) in tumor tissues were higher than those in normal tissues." (PMID 35642058, 2022). "Overexpression of OTUD1 increased the sensitivity of ESCC cells to DDP treatment, and the mutant lost this ability, which demonstrated that the tumor‐suppressive effect of OTUD1 is dependent on its enzymatic activity." (PMID 33898171, 2021). "This non-proteolytic ubiquitination can be reversed by the binding and interaction between deubiquitinase OTUD1 and YAP1; OTUD1 decreases YAP1 stability, and attenuates the cell proliferation and tumor-growth activity of YAP1." (PMID 32390875, 2020). "Knockdown of OTUD1 increases the sensitivity of tumour cells to the BH3-mimetic inhibitor ABT-263, while overexpression of OTUD1 increases tumour cell tolerance of ABT-263." (PMID 31467488, 2019). "In the absence of IR, upregulating OTUD1 or silencing SLC25A11 did not significantly affect tumor growth." (PMID 40664662, 2025). "OTUD1 may inhibit the proliferation, migration, and invasion of NSCLC cells by deubiquitinating and stabilizing the tumor suppressors KLF4 and FHL1." (PMID 41050073, 2025).
tumor (continued). "Thus, OTUD1 seems to be a central regulator of MCL1, cell death pathways, mitochondrial OXPHOS, and chemoresistance of tumor cells." (PMID 36829909, 2023). "The tumor volume and weight of the oe-OTUD1-treated mice were significantly reduced with or without erlotinib treatment." (PMID 36182943, 2022). "Importantly, the expressions of OTUD1 and KEAP1 were significantly correlated in the normal kidney cortex; however, the positive correlation was lost in the tumor." (PMID 35941131, 2022). "IHC analysis of OTUD1 in the KIRC tissue microarray (KIRC tumor n=38, nontumor tissue n=38) also showed that OTUD1 was downregulated in the tumor tissues (P =0.004)." (PMID 35280681, 2022). "In contrast, OTUD1 depletion increased the chemoresistance of ESCC xenografts to DDP but did not affect tumor growth." (PMID 33898171, 2021). "Here OTUD1-depleted 4T1 cells showed increased spontaneous lung metastasis without affecting primary tumor growth." (PMID 29235476, 2017). "Conversely, in the same limited cell number injection assay we observed that ectopic expression of OTUD1-wt, but not the CA mutant, inhibited tumor incidence and growth and prolonged latency after injection of 102, 103, 104 but not 105 cells." (PMID 29235476, 2017). "Although silencing of endogenous OTUD1 strongly increased the capacity of MCF10A (RAS) cells to form tumor spheres, ectopic expression of OTUD1-wt, but not the CA mutant form, greatly reduced this." (PMID 29235476, 2017). "Conversely, lentiviral-mediated expression of wt OTUD1, but not the CA mutant, significantly reduced the number of tumor-like colonies." (PMID 29235476, 2017). "Depletion of endogenous OTUD1 potentiated the capacity of RAS transformed MCF10A cells to form tumor organoids in 3D Matrigel but did not inhibit tumor cell survival and proliferation under standard 2D culture conditions." (PMID 29235476, 2017). "However, OTUD1 exhibited tumor-promoting effects in PDAC cells, which may result from tissue specificity, and more studies are still needed to confirm the link between OTUD1 and PDAC further." (PMID 41050073, 2025). "In addition, OTUD1 and ASK1 subcellular localization was analyzed in the xenograft tumor tissues." (PMID 38351029, 2024). "Alternatively, OTUD1 may inhibit the proliferation, migration, and invasion of NSCLC cells by deubiquitinating and stabilizing the tumor suppressors KLF4 and FHL1, but the authors did not delve into the ubiquitination site of KLF4." (PMID 41050073, 2025).
cancer (18 papers, 2017 to 2025). A tumor composed of atypical neoplastic, often pleomorphic cells that invade other tissues. "The accumulation of Yes-associated protein (YAP) in the nucleus has been associated with cancer, and OTUD1 has been identified as a DUB that cleaves the K63-type polyUb chain of YAP and as a negative regulator of the nuclear translocation and activity of YAP." (PMID 41050073, 2025). "Meanwhile, OTUD1 is lost in multiple types of human cancer 22 and closely associated with cell survival and apoptosis." (PMID 35280681, 2022). "Another aspect that deserves discussion is the broad and frequent loss of OTUD1 expression in human cancers." (PMID 29235476, 2017). "In addition, a flow cytometric cell sorting assay showed that loss of OTUD1 obviously decreased the cancer stem cell ratio." (PMID 38351029, 2024). "This study illustrates that OTUD1 can promote apoptosis in cancer cells by activating caspase-independent and caspase-dependent apoptotic pathways." (PMID 41050073, 2025). "In this review, we comprehensively summarize the roles of seven DUBs with OTU structural domains in cancer progression and antiviral immune responses, including OTUD1, OTUD2, OTUD3, OTUD4, OTUD5, OTUD6A, and OTUD6B." (PMID 41050073, 2025). "OTUD1 has emerged as a critical regulator of various biological processes, including cancer progression, antiviral defense, and inflammatory responses." (PMID 40007014, 2025). "Previous cancer research involving the OTUD1 protein has mainly focused on its canonical deubiquitinase activity." (PMID 38351029, 2024). "OTUD1 has been reported to be involved in inflammatory responses 16, 19, 41, innate immunity 17, drug resistance in cancer." (PMID 39309432, 2024). "OTUD1 is a deubiquitinating enzyme involved in many cellular processes, including cancer and innate immune signaling pathways." (PMID 37872170, 2023). "Our findings add scientific content to understanding the regulation of the immune checkpoint molecule FGL1 and the functional roles of OTUD1-mediated deubiquitination in cancer immunology." (PMID 37872170, 2023). "Accumulating evidence suggests that OTUD1 is a critical regulator of gene transcription, cancer metastasis and chemoresistance." (PMID 37872170, 2023). "In other papers suggesting a link between OTUD1 and cancer, OTUD1 reportedly deubiquitinates and stabilizes Krüppel-like factor 4 (KLF4), a zinc finger transcription factor that regulates proliferation, differentiation, apoptosis, and reprogramming." (PMID 36829909, 2023). "We found that CD68, TNFα, and OTUD1 expression was inversely correlated with the overall survival of cancer patients." (PMID 37872170, 2023). "Collectively, these findings indicate that OTUD1 functions as a crucial regulator of cancer progression, antiviral host defense responses, and inflammatory responses." (PMID 35941131, 2022). "The mechanism of OTUD1 in regulating cancer progression is still unclear and needs to be further studied." (PMID 35280681, 2022). "We found that cotransfection with siPTEN and siOTUD1 attenuated the increase in phosphorylated AKT, VCAM1 and CXCL8 and cancer cell proliferation induced by knockdown of OTUD1 alone." (PMID 35280681, 2022). "The survival analysis was used to determine the relationship between OTUD1 expression levels and the survival rate of cancer patients." (PMID 31467488, 2019). "Taken together, these results show that OTUD1 regulates sensitivity to a BH3-mimetic compound in different cancer cells." (PMID 31467488, 2019). "Next, we tested the relationship between OTUD1 expression levels and the survival rate of cancer patients." (PMID 31467488, 2019). "We subsequently examined the mitigating effect of OTUD1 on cancer stemness in vivo employing subcutaneous injections." (PMID 29235476, 2017).
cancer (continued). "It is suggested that the cancer-inhibitory effect of OTUD1 may be related to regulating the iron transport process." (PMID 41050073, 2025). "The research on OTUD1 and cancer has become increasingly close in recent years." (PMID 41050073, 2025). "OTUD1 negatively regulates the cell cycle to inhibit the abnormal proliferation of cancer cells, since OTUD1 interacts with phosphatase and tensin homolog (PTEN), a negative regulator of the AKT (also known as protein kinase B) and NF-κB signaling pathways, and regulates its stability." (PMID 36829909, 2023). "We also showed that PTEN ablation could attenuate the decrease in phosphorylated AKT, VCAM1 and CXCL8 and cancer cell proliferation mediated by overexpression of OTUD1 in 786-O cells." (PMID 35280681, 2022). "We showed that knockdown of OTUD1 promoted cancer cell growth in both 786-O and ACHN cells." (PMID 35280681, 2022). "qRT-PCR analysis indicated upregulation of cancer stem cell markers and EMT genes in OTUD1-depleted 4T1 lung-metastatic nodules when compared with control group, again suggesting that OTUD1 functions to oppose cancer stemness and EMT-related gene-expression programs." (PMID 29235476, 2017). "OTUD1-silenced cancer cells show mesenchymal and stem-cell-like characteristics." (PMID 29235476, 2017). "Given the role of OTUD1 in the regulation of metastasis, we investigated the possibility that OTUD1 might be a relevant factor in late-stage cancer." (PMID 29235476, 2017). "High levels of OTUD1 inhibit cancer stemness and shut off metastasis." (PMID 29235476, 2017). "Notably, OTUD1 has been implicated in modulating antifungal innate immunity through the deubiquitination of CARD9, while its deficiency in various human cancers is strongly linked to cell survival, apoptosis, and the inhibition of cancer progression by triggering immunogenic cell death." (PMID 40007014, 2025). "Finally, to investigate the involvement of OTUD1 in human diseases, we analyzed cancer databases." (PMID 35941131, 2022). "Next, we wondered whether OTUD1 inhibits cancer cell growth through PTEN in ccRCC cells." (PMID 35280681, 2022). "Moreover, the development of inhibitors of OTUD1 might also help to investigate the role of OTUD1 in vitro and in vivo cancer models." (PMID 31467488, 2019). "We proposed that OTUD1 could be considered as a therapeutic target for curing these cancers." (PMID 31467488, 2019). "However, it has also been suggested that OTUD1 may be an oncogene in some cancers." (PMID 41050073, 2025). "Together, these findings suggest that OTUD1 is a suppressor of YAP signaling and is involved in the progression and chemoresistance of cancer cells." (PMID 36829909, 2023). "OTUD1 also regulates the sensitivity to a BH3-mimetic compound, ABT-263, in cancer cells, and attenuates the synergistic effect of an anticancer medicine, sorafenib." (PMID 36829909, 2023). "Therefore, OTUD1 may be selectively released and eliminated from the cancer cells by exomes." (PMID 36829909, 2023). "Although the details remain enigmatic, in a comparison of cancer exosome-transfected OK113 normal primary oral keratinocytes with untransfected cells, OTUD1 was identified as one of the decreased genes altered by exogenous exosomes." (PMID 36829909, 2023). "OTUD1 is a deubiquitylase belonging to the OTU family and has been detected in multiple types of human cancers." (PMID 36182943, 2022). "Taken together, these results show that OTUD1 attenuates the synergistic effect of Sorafenib and BH3 mimetic compound in cancer cells." (PMID 31467488, 2019).